BRAF (B-Raf proto-oncogene, serine/threonine kinase)
Diseases named in the same sentence as BRAF in open-access papers (continued):
Sharing a sentence is not in itself a finding about the gene and the disease.
melanoma (continued). "Furthermore, the inhibition of mTOR causes strong synergism with the BRAF inhibitor in BRAF inhibitor-resistant melanoma." (PMID 36014370, 2022). "However, intra-tumor heterogeneity is a well-established biological characteristic of human malignancies, including melanoma, affecting the predictiveness of tissue BRAF/NRAS mutational testing." (PMID 35804825, 2022). "Interestingly, treatment with the AT2R antagonists PD123319 and EMA401 inhibits angiogenesis, melanoma cell growth, and increases the effect of BRAF and MEK inhibitors in cells with BRAF V600E mutations." (PMID 35574555, 2022). "While they have demonstrated cytotoxicity in many cell lines, our finding of increased sensitivity in BRAF V600E mutated cell lines which includes almost all the melanoma cell lines in our dataset may warrant further investigation." (PMID 35525914, 2022). "In addition, the loss of miR-200c, a tumor suppressor in melanoma, seems to shorten the distant metastasis-free survival only in BRAF V600 mutated tumors." (PMID 35326682, 2022). "Approximately 50% of melanomas harbor mutations at position 600 of the BRAF gene (V600), the majority of which involve the substitution of valine by glutamic acid (V600E), resulting in constitutively active BRAF." (PMID 35879777, 2022). "As for the energy metabolic pathways involved in the early phases of melanoma pathogenesis, the key process is represented by glycolysis, and after the occurrence of BRAF mutations, the stimulation of transcription factors acting as key regulators of such process makes it even more effective." (PMID 35805902, 2022). "LXH254 may thereby help overcome intrinsic and acquired resistance to BRAF-targeted therapy in BRAFV600-mutated melanomas and be a novel therapeutic approach for NRAS-mutated patients." (PMID 35380338, 2022). "In detail, in our study, the downregulation of miR-125b, miR-200c and miR-205 was observed in primary melanomas that further metastasized (distant and lymph node metastasis) and in primary tumors of patients who died of melanoma, for both the BRAF WT and BRAF mutated subsets." (PMID 35326682, 2022). "However, increased PI3K/AKT pathway activation, as documented in patients with melanoma harboring BRAF V600K mutations, correlated with high tumor mutational load and improved immunotherapy outcomes." (PMID 36522538, 2022). "It is also indicated in combination with dabrafenib for adjuvant treatment of patients with Stage III melanoma following complete resection, advanced non-small cell lung cancer, and locally advanced or metastatic anaplastic thyroid cancer with BRAF V600 mutation." (PMID 35130943, 2022). "Although BRAF V600E is a dominant driver of mutations that are widely associated with melanoma aggressiveness, a small portion of resistant melanomas take advantage of the activation of the compensatory PI3K–Akt signalling cascade sustained by different genetic alterations." (PMID 35335966, 2022). "Most cases are sporadic, and various genetic mutations are involved in melanoma development, with the somatic activating mutations in the proto-oncogene B-Raf and v-Raf murine sarcoma viral oncogene homolog B (BRAF) gene (BRAF V600E) remaining the most significant ones." (PMID 35911362, 2022). "Moreover, mutation of BRAF were frequently identified in various cancers, including melanoma, non-Hodgkin lymphoma, colorectal cancer, thyroid carcinoma, non-small cell lung carcinoma." (PMID 36187840, 2022). "Here, we strengthened this observation by using alternative murine (D4M.3A, B2905, B16F10) and human (131/4-5B1, A375, WM115) melanoma models and clinical samples that present different origins, mutations (BRAF, PTEN, etc.), and responsiveness to immunotherapy." (PMID 35980743, 2022). "BRAF mutated melanoma accounts for over 50% of melanoma, of which V600E mutant represents 70%–90%." (PMID 36034784, 2022). "In melanomas, BRAF is most commonly mutated, along with other kinases including NRAS and NF1." (PMID 35560144, 2022).
melanoma (continued). "In contrast, many researchers reported that pBRAF, detected in the melanoma with acquired resistant to BRAF inhibitors, is caused by paradoxically activation of upstream RTK or RAS through ERK1/2 feedback mechanism, suggesting new strategies for UC chemotherapy." (PMID 36477686, 2022). "However, BRAF mutations mainly occur in the progression of melanoma and rarely occur in the advanced stages, suggesting that this pathway plays a role in the initiation and progression of melanoma." (PMID 36185198, 2022). "For example, laser microbiopsy may be valuable in applications such as determining BRAF mutation status for melanoma." (PMID 36530344, 2022). "Thirdly, the co-existing lung disease status and the detailed genetic information of primary cancer (such as RAS mutation status in CRC, BRAF mutation in melanoma, and so on) remained unknown, which disenabled more precise epidemiological data on sLM." (PMID 35406378, 2022). "BRAF mutations are frequently observed in melanoma, thyroid cancer, and others." (PMID 36585710, 2022). "In addition, BRAF inhibitor plus MEK inhibitor combination therapy is also available for malignant melanoma patients with positive BRAF mutation (BRAFV600E/K mutation)." (PMID 35163049, 2022). "Genomic sequencing has identified oncogenic BRAF mutations in greater than 50% of melanoma tumors." (PMID 35785205, 2022). "Dabrafenib was approved by the FDA on 29 May 2013 for the treatment of BRAF V600E mutation-positive advanced melanoma disease." (PMID 36204232, 2022). "Possibly also combinations of BRAFi therapy and immune checkpoint inhibitors in patients with BRAF-mutated metastatic melanoma may change advanced melanoma treatment in the future." (PMID 35456332, 2022). "Importantly, MITFlowAXLhigh expression was shown to be common in BRAF mutated melanoma and has been identified in patients who relapsed following BRAF and MEK inhibitors treatment, thereby indicating that this signature results in a drug resistant phenotype." (PMID 36119516, 2022). "Inhibitor of differentiation protein 3 (ID3) is another player highly involved in phenotype switching; the transcription profiling of 21 BRAF-mutated melanomas revealed an upregulation of ID3 in BRAF inhibitor (BRAFi)-resistant tumors compared to treatment-naïves." (PMID 36551603, 2022). "Melanomas are the third most common cause of cerebral metastases, preceded only by non-small-cell lung cancer and breast carcinomas; moreover, more than 50% of patients with metastatic melanoma have a specific mutation in the serine/threonine kinase BRAF." (PMID 35806253, 2022). "BRAF-mutated melanoma is known to possess high glycolytic activity." (PMID 36034784, 2022). "Well-known examples are the RAS-activating mutations in BRAF actionable melanoma or the T790M resistance mutation in non-small cell lung cancer (NSCLC) under therapy with first or second generations tyrosine kinase inhibitors (TKIs) directed against the EGFR receptor." (PMID 36139547, 2022). "Neurofibromin 1 (NF1), a tumour suppressor gene encoding a negative regulator of RAS, is the most frequently mutated gene in sun-exposed malignant melanoma, after BRAF and NRAS, being associated with a high risk of metastasis and a high rate of treatment failure." (PMID 35334544, 2022). "Moreover, the BRAF mutation is present in almost 50% of melanoma cases, and in more than 90% cases, BRAF harbors the V600E point mutation." (PMID 35163615, 2022). "Yet, these studies usually only included BRAF V600E and V600K [Combi-D (dabrafenib/trametinib) [4••] and Columbus (encorafenib/binimetinib) [3••] or only BRAF V600E [CoBRIM (vemurafenib/cobimetinib) [9••] mutated melanomas." (PMID 35380338, 2022). "In melanoma, BRAF‐activating mutations are approximatively present in 50% of all tumours." (PMID 36065138, 2022). "Finally, TRIAL 3 evaluated the effectiveness of vemurafenib 960 mg twice daily in patients with metastatic melanoma BRAF V600E mutation-positive melanoma, with brain metastasis." (PMID 35742834, 2022).
melanoma (continued). "Moreover, Vem, a promising drug targeting BRAF V600E mutation, is compromised by acquired resistance in V600E melanoma." (PMID 36034784, 2022). "Among the three isoforms of RAF (ARAF, BRAF, and CRAF), mutations in BRAF, especially at the V600 residue (e.g., V600E) in the activation loop, are frequently observed in several types of cancer, including melanoma, papillary thyroid cancer, and colorectal cancer." (PMID 36224343, 2022). "Previous studies have shown a direct link between skin cancer and mutated BRAF kinase accounting for 50% of total melanomas, decreasing its expression could benefit in controlling the cancer." (PMID 36014478, 2022). "Because BRAF inhibitor resistance in BRAF V600E melanoma is associated with an immunosuppressed tumor microenvironment and consequent tumor immune evasion we tested all three isogenic melanoma models for increased levels of cell-surface PD-L1 expression by flow cytometry." (PMID 36358868, 2022). "The BRAF mutation V600E, which correlates with a poor prognosis in skin melanoma patients, has been used for designing a CRISPR/Cas9 system that specifically targets the mutated BRAF gene in A375 and G361 melanoma cell lines and mediates cleavage upon stimulation with blue light." (PMID 36139356, 2022). "Targeting metabolic pathways and the mTOR pathway may facilitate the development of new therapies to overcome Vem-resistance problems in BRAF mutated melanoma." (PMID 36034784, 2022). "Current treatments for melanoma focus on mutated BRAF and its downstream pathways." (PMID 36060947, 2022). "Twenty-two patients had a melanoma harboring BRAF mutation and 39 patients were BRAF wild-type; in 4 patients, the BRAF mutational status was unknown." (PMID 36016960, 2022). "Therefore, in this study, we evaluated, for the first time, the therapeutic potential of G18.EE and its fractions on BRAF-mutated melanoma cells." (PMID 35684471, 2022). "In addition, the relationship between RAS84 expression and RAS pathway gene mutations is different in cancers with very high BRAF mutation levels, such as thyroid carcinoma and melanoma, which score as only moderate for RAS pathway activity." (PMID 36163168, 2022). "Discovering the expression of this specific biomarker in both cancers has unleashed the potential for targeted molecular therapies.In patients with BRAF-mutated melanoma, adopting a combined targeted treatment approach has shown a dramatic increase in overall survival." (PMID 36589179, 2022). "In addition, the most frequent and well-known genetic alterations occurring in melanoma are linked to the BRAF, NRAS, KIT, and NF1 genes." (PMID 36431075, 2022). "Additionally, wobble U34 modifications catalyzed by ELP3/CTU1/2 have been shown to drive melanomas that express mutated BRAF, with subsequent resistance to anti-BRAF therapy caused by U34-dependent codon-biased translation of metabolic proteins." (PMID 35327975, 2022). "The observed increase of tumor cellularity in progressed melanoma tumors could be either a result or a cause of the escape from BRAF/MEK-inhibition." (PMID 35058553, 2022). "However, approximately 70% of melanomas harbor BRAF mutations, whereas BRAFV600E and BRAFV600K account for 80 ~ 90% and 10 ~ 20% of all BRAF mutations, respectively, making it a therapeutic target in melanoma." (PMID 36209184, 2022). "Moreover, patients with BRAF mutated stage III melanoma had a 77% higher three-year recurrence rate." (PMID 35456332, 2022). "However, we believe that AntiPD1 monotherapy remains a central treatment in the management landscape of mutated BRAF melanoma patients and we believe that studies such as this can help frame its right place in the therapeutic decision-making algorithm." (PMID 36046043, 2022). "We report on a rare case of a young patient with an intrahemispheric pleomorphic tumor, initially misdiagnosed and treated as a BRAF-mutated melanoma of unknown primary." (PMID 35198980, 2022).
melanoma (continued). "Melanoma is a genetically complex disease and the molecular context of BRAF, RAS and c-kit gene mutation may affect the response to targeted treatment and even immunology-based therapies in man." (PMID 35202309, 2022). "BRAF mutations are the most common alterations found in melanoma." (PMID 36431906, 2022). "This work focuses on the peculiar contribution made by molecular dynamics simulation and in silico tools, in the choice of an effective second line therapy for a BRAF-mutated melanoma patient who developed resistance to the undergoing targeted therapy with BRAF/MEK inhibitors." (PMID 36077693, 2022). "MEK and BRAF inhibitors reverted BRAF-mutated melanoma-induced DC suppression in vitro." (PMID 35328639, 2022). "Notably, 26.2%, 5.5%, and 1.2% of patients with cutaneous, acral, and mucosal melanomas, respectively, tested positive for BRAF mutation." (PMID 35896505, 2022). "Approximately 40–50% of melanomas harbor a BRAF V600 mutation and, thus, may respond to treatment with BRAF ± MEK inhibitors." (PMID 35625881, 2022). "BRAF mutations were detected in 16 melanomas, of which 50% were valine (V) to lysine (K) substitutions in codon 600, 31.2% were V to glutamic acid (E) substitutions in codon 600, and 18.8% were other BRAF hotspot mutations." (PMID 36064728, 2022). "At present, BRAF inhibitors have been approved for the treatment of various types of cancer harboring BRAF class 1 mutations: For patients with advanced melanoma the BRAF and MEK inhibitor combinations dabrafenib/trametinib, encorafenib/binimetinib and vemurafenib/cobimetinib can be employed." (PMID 36275468, 2022). "Therefore, a basket clinical trial was conducted in patients harboring BRAF V600E mutations and cancers in tissues other than those of melanoma patients." (PMID 35893795, 2022). "Previously, the BRAF V600E mutation focused on malignant tumours, where the prevalence was approximately 74.6% for papillary thyroid carcinoma, 7.4% for colorectal cancer, and 60% for melanomas." (PMID 36428683, 2022). "Although, oncogenic BRAF and NRAS mutations are usually mutually exclusive, they co-occur in approximately 7% of untreated melanoma and NRAS mutations confer resistance in 27% of BRAFV600-mutant melanoma patients who progress on combination BRAF and MEK inhibitor therapy." (PMID 35494035, 2022). "For example, in BRAF-mutated malignant melanoma, the combination of BRAF inhibitor encorafenib and MEK inhibitor binimetinib was more effective than single agents, showing significant effect in delaying the onset of drug resistance and improving the overall survival rate of patients." (PMID 35965583, 2022). "Similarly, BRAF mutation driven melanoma exhibited resistance to BRAF inhibitors vemurafenib or dabrafenib due to overexpression of Mcl-1." (PMID 36045907, 2022). "Both primary lesions could easily have been missed and thus the mucosal lesion would erroneously be regarded as a primary BRAF-mutated mucosal melanoma." (PMID 34142226, 2022). "Several controversies remain in the field of BRAF-mutated melanoma treatment." (PMID 35954441, 2022). "In 2014, the FDA and one year later, the European Medical Agency (EMA) approved pembrolizumab and nivolumab, both anti-PD-1 blocking antibodies, to treat advanced/unresectable melanoma in a second line, after the failure of ipilimumab or BRAF inhibitors (in case of BRAF mutation)." (PMID 36289790, 2022). "Strikingly, 50% of melanomas harbor BRAF V600E mutation that consists in the substitution of valine for glutamic acid at codon 600, that results in the constitutive activation of the serine/threonine kinase activity of BRAF." (PMID 35327519, 2022). "Interestingly, a systematic study of the BRAF AS landscape in melanoma has revealed that BRAF is often mutated concurrently with BRAF RBD deletions." (PMID 35883549, 2022).